LDB2 (LIM domain binding 2)
Description:
Transcription cofactor. Binds to the LIM domain of a wide variety of LIM domain-containing transcription factors.
Synonyms: LDB-2; CLIM1; LDB1
Tractability: Antibody: its Gene Ontology location is reachable by antibodies, with high confidence. PROTAC: UniProt records ubiquitination sites on it; ubiquitination databases record sites on it.
Gene: Protein-coding gene on chromosome 4 (16,501,534 to 16,898,924, reverse strand). Ensembl gene ENSG00000169744.
Subcellular location: Nucleus
Subcellular location (Human Protein Atlas): Nucleoli; Nucleoplasm; Plasma membrane
Gene Ontology:
Molecular function: protein binding; LIM domain binding; transcription coregulator activity
Biological process: negative regulation of transcription by RNA polymerase II; nervous system development; positive regulation of transcription by RNA polymerase II; regulation of cell migration; regulation of kinase activity
Cellular component: nucleolus; nucleoplasm; nucleus; cell leading edge; transcription regulator complex
Genetic constraint (gnomAD): Loss-of-function variants: 9 observed, 36.13 expected, observed/expected ratio (o/e) 0.25, 90% interval 0.15 to 0.44. The upper end of that interval is the gene's LOEUF score, 0.44, which puts it in group 1 of 6, group 1 being the genes least tolerant of losing a copy. Missense variants: 320 observed, 453.76 expected, observed/expected ratio (o/e) 0.71, 90% interval 0.64 to 0.77. Synonymous variants: 153 observed, 169.03 expected, observed/expected ratio (o/e) 0.91, 90% interval 0.79 to 1.03.
Homologues: Orthologues: chimpanzee LDB2 (100% identical), guinea pig LDB2 (99% identical), mouse Ldb2 (98% identical), macaque LDB2 (95% identical), rabbit LDB2 (95% identical), tropical clawed frog ldb2 (93% identical), zebrafish ldb2a (87% identical), pig LDB2 (80% identical), rat Ldb2 (80% identical), zebrafish ldb2b (70% identical), Drosophila melanogaster Chi (64% identical), Caenorhabditis elegans ldb-1 (34% identical). Paralogues in human: LDB1 (77% identical).
Diseases named in the same sentence as LDB2 in open-access papers:
LDB2 is named in the same sentence as 23 diseases in open-access papers, as found by Europe PMC text mining. Sharing a sentence is not in itself a finding about the gene and the disease. The quoted sentences say what the papers report.
liver cancer (5 papers, 2017 to 2023). An epithelial or non-epithelial malignant neoplasm that arises from the liver. "LDB2 also works in transcriptional regulation and has been found to have a lower expression in liver cancer as well." (PMID 34791179, 2022). "NONHSAT095695.2, ENST00000552253.1 and ENST00000588495.5 regulated LDB2, which inhibits liver cancer cell proliferation and migration via suppressing the expression of HEY1." (PMID 33075110, 2020). "To explore the function of LDB2 in liver cancer, we deleted it in HCC samples." (PMID 29212240, 2017). "had demonstrated LDB2 could inhibit proliferation and migration in liver cancer cells." (PMID 36473369, 2023). "However, LDB2 has been shown to inhibit liver cancer cell proliferation and migration, functioning as a tumor suppressor, while ATF6 has been linked to the induction of intestinal dysbiosis and immune activity associated with the development of colorectal cancer." (PMID 33075110, 2020). "The results demonstrated that the expression of FCER1G, PFN1, ACTG1, PABPC1, CALM1, and RPS8 was significantly upregulated in the liver cancer cells, whereas KLRB1, LDB2, and FYN exhibited the opposite trend." (PMID 37397471, 2023).
atherosclerosis (4 papers, 2009 to 2024). A disease characterized by the build-up of fatty material and calcium deposition in the arterial wall resulting in partial or complete occlusion of the arterial lumen. "Previous studies have shown that LDB2 plays an important role in atherosclerosis development and targets carotid artery disease by inhibiting the activity of transendothelial migration in the leukocyte pathway." (PMID 38200081, 2024). "We also identified a putative high-hierarchy regulator of the A-module, LDB2, which was robustly expressed in all major lesion cell types both in lesion-free and in late atherosclerosis lesions." (PMID 19997623, 2009). "In summary, LDB2 was expressed by all three major atherosclerosis cell types; before lesion formation and in early lesions primarily in the endothelium and in late lesions, mainly in macrophages/foam cells but also in SMCs." (PMID 19997623, 2009). "Third, the LIM Domain Binding Factor 2 gene (LDB2), which encodes for a protein playing a crucial role in lymphocyte migration and atherosclerosis, has been shown to have a strong relationship with daily body weight gain in other species, such as poultry, as derived from GWAS studies." (PMID 35454235, 2022). "The Stockholm Atherosclerosis Gene Expression (STAGE) study involved from 2009 performed whole-genome transcriptome analyses in five tissues and identified an atherosclerosis module that included LIM domain-binding protein 2 (LDB2) as a high-hierarchy regulator." (PMID 36139449, 2022). "We found an atherosclerosis module (A-module) consisting of 128 genes, enriched with genetic risk for CAD, involving transendothelial migration of leukocytes (TEML) and LIM domain binding 2 (LDB2) as its high-hierarchy regulator." (PMID 19997623, 2009). "Thus, the A-module appears to be important for atherosclerosis development and, together with LDB2, merits further attention in CAD research." (PMID 19997623, 2009). "However, the final verdict on LDB2 as an important regulator of atherosclerosis development remains to be determined." (PMID 19997623, 2009). "The A-module and LDB2 are attractive targets for treatments to modulate TEML and atherosclerosis development." (PMID 19997623, 2009). "Taken together, the functional validation supports a role for LDB2 in TEML and atherosclerosis development." (PMID 19997623, 2009). "Our findings suggest that the A-module, including LDB2, is important in the regulation of TEML and in atherosclerosis development." (PMID 19997623, 2009). "LDB2 has not previously been related to CAD or atherosclerosis." (PMID 19997623, 2009).
lung adenocarcinoma (2 papers, 2023 to 2024). A carcinoma that arises from the lung and is characterized by the presence of malignant glandular epithelial cells. "High expression levels of WARS were found in high microsatellite-instable gastrointestinal adenocarcinomas, associated with poor prognosis, while a decreased expression of LDB2 was associated with a more favorable outcome in lung adenocarcinoma patients." (PMID 37794510, 2023). "Recent in vitro studies showed that LDB2 inhibited the proliferation and migration of hepatocarcinoma cells and that LDB2 expression can be upregulated by the m6A reader YTH Domain Containing 2 (YTHDC2) in lung adenocarcinoma to inhibit the proliferation of tumor cells." (PMID 38200081, 2024).
lung carcinoma (2 papers, 2020 to 2023). "In this research, the authors found that the expression of LDB2 was significantly reduced in lung cancer tissues and negatively correlated with miR-96-5p expression." (PMID 36473369, 2023). "Summarily, these results indicate LDB2 plays an important role in regulating the proliferation, migration, and invasion of the lung cancer cell." (PMID 36473369, 2023). "•MiR-96-5p/LDB2 regulates cellular behaviors through ERK1/2 signaling pathway in lung cancer H1299 cell." (PMID 36473369, 2023). "The authors detected the expressions of LDB2 and miR-96-5p in 65 pairs of lung cancer tissues and their corresponding para-cancerous tissues and cell lines by qRT-PCR." (PMID 36473369, 2023). "In this study, the authors analyzed the relative expression level of LDB2 and miR-96-5p in lung cancer tissues." (PMID 36473369, 2023). "In this study, the authors found miR-96-5p was high-regulated in lung cancer tissues and negatively correlated with LDB2 expression." (PMID 36473369, 2023). "Knockdown or overexpression of LDB2 could promote or inhibit the proliferation of lung cancer cells, which was consistent with the results of Zhai's research." (PMID 36473369, 2023). "All findings suggested that LDB2 was down-regulated by miRNA-96-5p inhibited cell proliferation, invasion, and metastasis in lung cancer H1299 cells, which can provide a new direction for the future diagnosis and treatment of lung cancer." (PMID 36473369, 2023). "In this study, the authors found that LDB2 was under-expressed in lung cancer tissues." (PMID 36473369, 2023). "The aim of this study is to investigate the potential role of LDB2 and miR-96-5p in lung cancer." (PMID 36473369, 2023). "Therefore, in the angiogenesis of lung cancer, whether LDB2 directly affects angiogenesis or acts on endothelial cells through the secretion of angiogenic factors by tumor cells needs to be further researched." (PMID 36473369, 2023). "Therefore, the authors found LDB2 was down-regulated by miRNA-96-5p and inhibited cell proliferation, invasion, and metastasis in lung cancer H1299 cells, these findings might provide a novel target for the diagnosis and treatment of lung cancer." (PMID 36473369, 2023). "MiR-96-5p may be to promote proliferation, invasion, and metastasis via targeting LDB2 and regulate cellular behaviors through the ERK1/2 signaling pathway in lung cancer." (PMID 36473369, 2023). "Besides, the expression of LDB2 was markedly lower in lung cancer cells than that in the normal bronchial epithelial cell line BEAS-2B." (PMID 36473369, 2023). "Together our results most clearly highlighted the importance of TEK, LDB2, ATF6 and UBQLN1 in NSCLC patient BE responses, underscoring the value of examining system-level gene interactions in order to better understand the determinants of lung cancer patient therapeutic responsiveness." (PMID 33075110, 2020). "LDB2 and ATF6 were not included in TCGA lung cancer datasets." (PMID 33075110, 2020).
mental disorder (2 papers, 2020 to 2021). A disease that has its basis in the disruption of mental process. "Collectively, the findings suggest that dysregulation in the gene expression controlled by the LDB2‐EGR axis underlies a pathogenesis of subset of mental disorders." (PMID 33656268, 2021). "The present study reveals a major molecular pathway that leverages LDB2 and immediate early genes, in the pathogenesis of mental disorders including schizophrenia and bipolar disorder." (PMID 33656268, 2021). "Multiple observations in the current study favor to the idea that LDB and LDB2‐mediated gene expression networks play a potential role in the pathogenesis of schizophrenia and other mental disorders, including bipolar disorder." (PMID 33656268, 2021). "We show here that Ldb2 knockout (KO) mice displayed multiple deficits relevant to mental disorders." (PMID 33656268, 2021). "This study investigates the role of LDB2 and transcriptional regulation exerted by the “LDB2‐EGR axis” in the pathogenesis of mental disorders." (PMID 33656268, 2021). "In summary, we present multiple lines of evidence that the “LDB2‐EGR” axis orchestrates the regulation of gene expression networks involving ARC and that a perturbation of this system is potentially related to the pathogenesis of mental disorders, such as schizophrenia and bipolar mania." (PMID 33656268, 2021).
bipolar disorder (1 paper, 2021). A disorder of the brain that causes unusual shifts in mood, energy, activity levels and the ability to carry out day-to-day tasks. "The Ldb2 KO mice exhibited hyperactivity in the home cage and open‐field test, the phenotype seen in multiple pharmacological and genetic animal models for schizophrenia or the manic state of bipolar disorder." (PMID 33656268, 2021).
colon cancer (1 paper, 2021). "A substantial fraction of the peaks was overlapped with those obtained with EGR1‐ChIP‐seq in three other cell lines H1ES (an ES cell line), HCT116 (a colon cancer cell line), and K562 (Fig EV5 A and B), further indicating interaction between LDB2 and EGR1 proteins." (PMID 33656268, 2021).
endometrial cancer (1 paper, 2021). Primary or metastatic malignant neoplasm involving the endometrium (mucous membrane that lines the endometrial cavity). "Indeed, ChIP‐seq signal for the EGR1 protein in cultured cell lines (ECC1: endometrial cancer; K562: erythromyeloblastoid leukemia) overlapped that of the LDB2 protein in neurosphere cells at the promoter region of ARC." (PMID 33656268, 2021).
hepatoma (1 paper, 2023). "Meanwhile, over-expression of LDB2 in hepatoma cells could significantly inhibit cell proliferation and migration, but the knockdown of LDB2 had the opposite effect." (PMID 36473369, 2023).
melanoma (1 paper, 2022). A malignant, usually aggressive tumor composed of atypical, neoplastic melanocytes. "For LDB2 and TMEM119 the highest mutation rate was in TCGA-SKCM, a melanoma study and was followed immediately by TCGA-UCEC." (PMID 34791179, 2022).
ovarian carcinoma (1 paper, 2023). A malignant neoplasm originating from the surface ovarian epithelium. "On the other hand, the model composed of GALNT9, UPF3A, WARS, and LDB2 incorrectly identified 1 out of 16 cancer cases (6.25%: ovarian cancer)." (PMID 37794510, 2023).
schizophrenia (1 paper, 2021). A major psychotic disorder characterized by abnormalities in the perception or expression of reality. "The LDB‐EGR system controls the expressions of many genes, including ARC/Arc, whose dysregulation may cause the abnormal spine physiology in Ldb2 KO mice and schizophrenia." (PMID 33656268, 2021). "The LDB2 gene is mapped at the breakpoint of a balanced chromosomal translocation seen in a patient with schizophrenia." (PMID 33656268, 2021). "Second, ablation of Ldb2 in a mouse resulted in pleiotropic behavioral abnormalities reminiscent of schizophrenia and bipolar mania." (PMID 33656268, 2021).
squamous cell carcinoma (1 paper, 2003). A carcinoma arising from squamous epithelial cells. "Expression of LMO4, LDB1, and LDB2 in squamous cell carcinomas has not been investigated." (PMID 12771919, 2003).
tumor (8 papers, 2010 to 2024). "These included cysteine/tyrosine-rich 1 (CYYR1) and LIM domain binding 2 (LDB2) genes that have been recently reported as associated with disease-free survival with higher expression in tumours that metastasized after 24 months vs. tumours that metastasized earlier." (PMID 23526956, 2013). "Moreover, more LDB2-deficient tumor cells entered into cell cycle." (PMID 29212240, 2017). "Moreover, LDB2 deficiency led to enhanced tumor propagation in mice." (PMID 29212240, 2017). "Most of these genes were reported to be associated with tumor metastasis, such as TDO2, CYTL1, and LDB2." (PMID 35982908, 2022). "In 88 paired samples, LRRK2, PECAM1, EPAS1, and LDB2 showed significant low expression in tumor samples, which was consistent with previous results." (PMID 32196072, 2020). "Through analysis of online data set of microarray about HCC samples, we found that LDB2 was remarkably downregulated in tumor cells, which suggests a tumor suppressor of LDB2." (PMID 29212240, 2017). "Summarily, our research demonstrates that LDB2 can inhibit tumor cell proliferation and migration by downregulating HEY1 expression." (PMID 29212240, 2017). "Summarily, these data indicate that LDB2 plays an important role on regulating proliferation and survival of tumor cells." (PMID 29212240, 2017). "Altogether, LDB2 inhibits tumor cell proliferation and migration by targeting HEY1." (PMID 29212240, 2017). "LDB2 deletion significantly promotes the proliferation and migration abilities of tumor cells." (PMID 29212240, 2017). "Collectively, LDB2-dificiency promotes tumor proliferation in vitro and in vivo." (PMID 29212240, 2017). "Consequently, LDB2 overexpression remarkably reduced xenograft tumor growth." (PMID 29212240, 2017). "However, our results showed that LDB2 is a tumor repressor in HCC, which indicated that there may be various roles of LDB proteins in different tumors." (PMID 29212240, 2017).
cancer (4 papers, 2003 to 2026). A tumor composed of atypical neoplastic, often pleomorphic cells that invade other tissues. "Recently, the role of LDB2 in cancer has attracted people's attention, but its role in tumors is still controversial." (PMID 36473369, 2023). "LDB1, the homologous protein of LDB2, has been widely explored such as erythroid differentiation, embryogenesis, and cancer development, but the biological role of LDB2 bearing 78% identity and 89% similarity to the LDB1 is largely unknown." (PMID 36473369, 2023). "Four carcinomas and two normal samples augmented a single 702 bp fragment of the LDB2 transcript." (PMID 12771919, 2003). "Further study showed that LDB2 could recruit the tumor suppressor protein BRD7 into the promoter of the tumor-promoting protein HEY1 and exert the anti-cancer effect." (PMID 36473369, 2023). "Although minimal reaction of LDB2 immunostaining was noted in inflammatory cells that infiltrated into the carcinoma tissues, carcinoma cells did not react (data not shown)." (PMID 12771919, 2003).
neurodegenerative disease (1 paper, 2023). A disorder of the central nervous system characterized by gradual and progressive loss of neural tissue and neurologic function. "Two of them—Nrxn3 and Ldb2—are hubs in the transcriptional module related to neurodegenerative diseases, i.e., Nrxn3 in P60 and P120, and Ldb2 in P120." (PMID 37355705, 2023).
LDB2 also shares sentences with these, for which no sentence is quoted: breast carcinoma (3 papers); colorectal cancer (2); adenoma (1); Coronary Artery Disease (1); ganglioglioma (1); oral carcinomas (1); prostate carcinoma (1).